ARID1A (AT-rich interaction domain 1A)
Diseases named in the same sentence as ARID1A in open-access papers (continued):
Sharing a sentence is not in itself a finding about the gene and the disease.
colorectal cancer (continued). "Additionally, we observed that the low-expression group exhibited a high mutational load, with FBXW7, SOX9, AMER1, SMAD4, ARID1A, and B2M being the most frequently mutated genes in colorectal cancer." (PMID 40170839, 2025). "Aurora A is a therapeutic target in ARID1A-deficient colorectal cancer cells." (PMID 40362376, 2025). "Sensitivity to G4 ligands was apparent in both OCCC and colorectal cancer cell line models, and in vivo studies suggest that G4 ligands could hold promise for treating ARID1A-deficient cancers." (PMID 40938753, 2025). "In line with the immunogenicity of ARID1A mutation, a more recent study in 417 colorectal cancer patients demonstrated that ARID1A mutation may define an immunologically active subgroup in patients with microsatellite stable (MSS) tumors." (PMID 36980292, 2023). "ARID1A has also been associated with impaired DNA damage repair, and, in colorectal cancer, ARID1A was enriched in patients who developed resistance to an anti-EGFR monoclonal antibody, suggesting it may play a role in resistance in this setting." (PMID 36077815, 2022). "ARID1A is frequently mutated in colorectal cancer (CRC) cells." (PMID 36249060, 2022). "Thus, ARID1B is required for chromatin accessibility regulation in ARID1A-deficient colorectal carcinoma cells and OCCCs." (PMID 36361605, 2022). "In colorectal cancer, loss of ARID1A expression was associated with a younger age." (PMID 32961530, 2020). "In colorectal cancer, loss of ARID1A expression was associated with younger age." (PMID 32961530, 2020). "In addition, CRISPR-mediated deletion of ARID1A in human colorectal cancer cells with KRAS mutations significantly reduced proliferation, accompanied by attenuation of MEK/ERK dependent transcriptional signaling." (PMID 32967217, 2020). "In colorectal cancer, it appears that loss of ARID1A in wild-type backgrounds may promote early tumorigenesis while loss of ARID1A in the background of mutations in APC or KRAS may inhibit tumor progression." (PMID 31217031, 2019). "It is thus likely that miR-31 overexpression, in addition to deletion, mutation or epigenetic disruption of this gene, may underlie ARID1A downregulation in both lung and colorectal carcinomas." (PMID 27528032, 2016). "Therefore, exploring the molecular basis of this downregulation could lead to the development of ways for treating ARID1A-deficient colorectal cancer." (PMID 35611248, 2022). "Thus, loss of ARID1A differentially affects colorectal cancer cell proliferation." (PMID 31217031, 2019). "In colorectal cancer (CRC) patients, mutations in the ARID1A gene occur in approximately 10% of cases." (PMID 41360780, 2025). "For example, in colorectal cancer, the loss of the BAF chromatin remodeler subunit ARID1A, a tumor suppressor, leads to the derepression of a specific set of HERVH loci, which in turn modulates BRD4-dependent transcription." (PMID 40618134, 2025). "ARID1A, a component of the SWI/SNF tumor suppressor complex, is frequently mutated in colorectal cancers (CRC)." (PMID 41319275, 2025). "It has been shown that alterations in ARID1A are associated with checkpoint gene expression and other markers of immunogenicity in MSS colorectal cancer." (PMID 39697230, 2024). "In detail, ARID1A downregulation has been reported to influence the proliferation of colorectal cancer cells and their resistance to chemotherapy." (PMID 38893181, 2024). "In KRAS-mutated colorectal cancers, trametinib leads to the attenuation of MEK/ERK pathways, similar to the effect of ARID1A loss in these cells." (PMID 36658200, 2023).
colorectal cancer (continued). "A study concerning exome sequencing of MSI colorectal cancers showed that the ARID1A gene exhibited more frequent short tandem repeats (STR) mutations, inferring MMR deficiency as the underlying cause of ARID1A mutations." (PMID 37366273, 2023). "Multiple studies have demonstrated that, in mouse embryonic fibroblast system and human colorectal cancer cell lines, ARID1A mediates chromatin accessibility, SWI/SNF binding, and deposition of H3K27Ac active histone marks at enhancers." (PMID 38275587, 2023). "There is an interesting observation because KEGG analyses discovered that genes with increased expression (ARID1A KO vs WT) were implicated in the Ras signalling, Rap signalling, PI3‐AKT signalling, MAPK signalling and colorectal cancer pathways." (PMID 36420658, 2022). "TNFα treatment stimulated ARID1A turnover in lung and colorectal cancer cells, A549 and HCT166 cells." (PMID 36435834, 2022). "The current study aimed to focus on the role of histone deacetylation in reduced ARID1A expression in colorectal cancer cell lines." (PMID 35611248, 2022). "The expression levels of ARID1A mRNA were determined using real-time quantitative PCR in colorectal cancer cell lines including HCT116, SW48, HT29, SW742, LS180, and SW480." (PMID 35611248, 2022). "In this study, we observed that R1989* was captured less frequently than D1850Tfs*33 and D1850Gfs*4, possibly because the study included a very high proportion of colorectal cancer cases, and reportedly, D1850fs is an ARID1A hot spot in colorectal cancer." (PMID 36371186, 2022). "Colorectal carcinoma cell lines with wild-type ARID1A (HCT15, HCT116, Colo320DM) and mutant ARID1A (RKO, SW48, LS180) were used." (PMID 36249060, 2022). "In colorectal cancer, loss of ARID1A located at enhancers leads to dramatic changes in chromatin accessibility, and influences the expression of MET in colorectal cancer cell growth and adhesion." (PMID 33125076, 2021). "Inhibition of Aurora A with a pan-selective kinase inhibitor, TCS-7010, in ARID1A-mutant colorectal cancer cells induced a G2/M phase arrest, followed by apoptosis." (PMID 33941852, 2021). "The downregulation of ARID1A is thought to induce colorectal carcinoma possibly through its regulation of proliferation and chemoresistance in colorectal cancer cells." (PMID 34671561, 2021). "ARID1A is instead overexpressed in many hepatocellular carcinomas, while the expression of this gene is reduced or lost in colorectal cancer." (PMID 33748136, 2021). "The Kaplan-Meier curve highlights the need for a larger number of patients to confirm the prognostic value of ARID1A expression in colorectal cancer." (PMID 32334542, 2020). "ARID1A and FBXW7 are well-established tumor suppressors and are found mutated at similar frequencies in sporadic- and colitis-associated colorectal cancers." (PMID 32697969, 2020). "Relationships between ARID1A expression and clinicopathological features was analyzed in patients with colorectal cancer." (PMID 32334542, 2020). "The ARID1A mRNA expression was examined in six colorectal cancer cell lines, SW48, SW742, HT29/219, HCT116, LS180, and SW480." (PMID 32334542, 2020). "For this purpose, we utilized a CRISPR/Cas9-mediated gene editing approach to delete a portion of the ARID1A gene in four colorectal cancer cell lines (COLO320DM, DLD1, HCT116, and HT29)." (PMID 31217031, 2019). "In colorectal cancer, it was shown that the activity of BAF-occupied enhancers is reduced in ARID1A-deficient cells and accompanied by a loss of the active H3K27ac mark (acetylation of lysine 27 on histone 3)." (PMID 31217031, 2019).
colorectal cancer (continued). "In colorectal cancer, the deletion of Arid1a in the background of Apc inactivation (which hyperactivates the Wnt pathway) blocked tumor formation." (PMID 31217031, 2019). "We identified that ARID1A is essential in specific contexts of colorectal cancers and was able to show mechanistically that KRAS-mutated colorectal cancer cells are especially dependent on the presence of ARID1A." (PMID 31217031, 2019). "To mimic ARID1A-deficient colorectal cancer, we used CRISPR/Cas9-mediated gene editing to inactivate the ARID1A gene in established colorectal cancer cell lines." (PMID 31217031, 2019). "In this study, we explored the role of ARID1A in transcriptional control of gene expression in colorectal cancer cells." (PMID 31217031, 2019). "Our work suggests that this interaction is especially relevant in KRAS-mutated colorectal cancers, where an attenuation of the MEK/ERK pathway mimics the effects of ARID1A loss in these cells." (PMID 31217031, 2019). "It has also been shown that a decreased ARID1A expression results in inhibition of 5-FU-induced apoptosis in colorectal cancer cell lines." (PMID 29681787, 2018). "In the current study, after confirming the synthetic lethal relationship between ARID1A and ARID1B in colorectal carcinoma proliferation, we uncovered the mechanistic basis underlying this phenomenon by examining chromatin accessibility across the genome." (PMID 28967863, 2017). "The ARID1A, BCR, CHD5, RPL22 and TSC2 genes were shared mutation targets in ovarian and colorectal carcinomas." (PMID 29296220, 2017). "In colorectal cancer (CRC), the frequency of ARID1A mutations is ~10%." (PMID 40369167, 2025). "Higher PD-L1 expressions are also seen in colorectal cancer due to low ARID1A expression." (PMID 40429787, 2025). "The experimental investigations of ARID1A inactivation in cellular and mouse models have revealed that ARID1A acts as a tumor suppressor during the initiation and progression stages of carcinogenesis in gynecological, liver, and colorectal cancer models." (PMID 41049615, 2025). "Among the MSS colorectal cancers, tumors with ARID1A mutations showed higher expression of immune-related molecules (PD-1, cytotoxic T-lymphocyte antigen 4 (CTLA4)) and cytotoxic T cell infiltration compared to the ARID1A wild type." (PMID 38893118, 2024). "AP-1 has the potential to be pro- or anti-tumorigenic depending on context and at least in ARID1A-null colorectal cancer cells, changes in genome regulation implicate AP-1 in controlling new gene networks associated with the regulation of oncogenic gene expression." (PMID 38473277, 2024). "ARID1A loss of function is quite common, mostly among gynecological cancers, and renders the ATR pathway indispensable for ARID1A-deficient cells, as demonstrated in vitro and ex vivo in colorectal cancer (CRC) cells." (PMID 38474014, 2024). "However, the relationship between the heterogeneous ARID1A expression and the immune response and immunotherapy efficacy in colorectal cancer (CRC) is still unclear." (PMID 38555560, 2024). "In colorectal cancer (CRC), the proliferation of KRAS-mutated cancer cell rely on ARID1A." (PMID 37727377, 2023). "Loss of ARID1A was found to have a significant correlation with the expression of IFN-γ and checkpoint genes (including PD-L1, CTLA4, and PDCD1) in microsatellite-stable colorectal cancer." (PMID 35198440, 2022). "ARID1A is an epigenetic regulator mutated in approximately 5% of non-hypermutated colorectal cancer tumors, however, its relationship with treatment response remains to be explored." (PMID 36117191, 2022). "Histone deacetylase inhibitors might provide a strategy to restore ARID1A expression and may bring benefits to the colorectal cancer patients with a broader range of genetic backgrounds." (PMID 35611248, 2022). "Clinicopathologic characteristics and ARID1A expression in patient samples of colorectal cancer." (PMID 36249060, 2022).
colorectal cancer (continued). "DNA methylation has been reported as an important regulator of ARID1A expression in colorectal cancer cell lines; however, the histone modification role in ARID1A suppression in colorectal cancer remains unclear." (PMID 35611248, 2022). "The tumor suppressive role of ARID1A was well-established in colorectal cancer." (PMID 35611248, 2022). "We discovered that ARID1A predicted poor prognosis in colorectal cancer patients." (PMID 34414106, 2021). "Only one previous study found a significant association between loss of ARID1A expression and overall survival in stage IV colorectal cancer, rather than in stage I-III patients." (PMID 32334542, 2020). "In addition, we further evaluated the relationship between ARID1A expression and overall survival in colorectal cancer patients." (PMID 32334542, 2020). "An additional study also demonstrated that Arid1a is protumoral rather than a tumor suppressor in colorectal cancer with Apc mutations." (PMID 33084574, 2020). "Furthermore, we confirmed that ARID1A itself is, indeed, mainly localized at enhancers in colorectal cancer cells where it acts as a co-factor at regions bound by AP1 transcription factors, which act downstream of the MEK/ERK pathway." (PMID 31217031, 2019). "ARID1A deficiency does not have a significant impact on colorectal cancer prognosis." (PMID 38275587, 2023). "However, there are few studies that investigated the incidence and clinicopathologic importance of ARID1A loss in colorectal cancer and available published results are not conclusive." (PMID 32334542, 2020). "However, the prognostic significance of ARID1A in colorectal cancer has yet to be determined." (PMID 30479693, 2018). "The nuclease benzonase was included in all buffers to minimize post-lysis DNA binding by cGAS, then Co-IP validated interactions between cGAS and SWI/SNF components such as ARID1A, SMARCA4 and SMARCC2 in colorectal cancer cells." (PMID 39080411, 2024). "This research suggests a unique genetic signature in MSI‐H colorectal cancer, emphasizing the importance of MMR‐related genes and revealing a potential role for ARID1A in influencing MMR processes." (PMID 38746969, 2024). "Conversely, ARID1A (BAF250A), a core member of the SWI/SNF complex, supports CXCL9 and CXCL10 expression in human colorectal cancer cells, resulting in enhanced recruitment of IFNγ-producing immune cells." (PMID 34385592, 2022). "We find that, ARID1A and EGFR-pathway genetic alterations are mutually exclusive across lung and colorectal cancers, further supporting a functional connection between these pathways." (PMID 36117191, 2022). "The expressional loss of ARID1A has been shown to trigger the initiation and progression of carcinogenesis in numerous types of cancers, including ovarian, breast, endometrial and cervical, breast, gastric, and colorectal cancers through several mechanisms that have not been fully elucidated." (PMID 34924820, 2021). "Suppression of TGFBR2 was evident in both human endometrial epithelial and HCT116 human colorectal carcinoma ARID1AKO cells, while TGFBR2 was upregulated in OV207 cells with induced ARID1A expression." (PMID 32483112, 2020). "Synthetic–lethal relationships exist for ATPases, BRG1 and BRM, in triple negative breast cancer, for accessory subunits of the SWI/SNF complex, ARID1A and ARID1B, in colorectal cancer and CHD1 with transcriptional regulator PTEN in prostate cancer." (PMID 30755246, 2019). "This work builds upon and expands existing knowledge about the interplay of ARID1A and AP1 transcription factors by showing its relevance in the development of a subset of colorectal cancers." (PMID 31217031, 2019).
colorectal cancer (continued). "Colorectal carcinoma cell lines with wild type (HCT15, HCT116, Colo320DM) and mutant ARID1A (LS180, RKO, SW48) were investigated." (PMID 31796878, 2019). "Specifically, we surveyed the genes most strongly reduced by ARID1B KD in ARID1A-/- cells and identified MET, a known driver of proliferation, as a potentially crucial target of ARID1A and ARID1B in colorectal cancer." (PMID 28967863, 2017). "In comparison to a recent analysis utilizing MutSigCV, our methodology identified other colorectal cancer related genes such as COL12A1, MLL2, FAT4m and ARID1A." (PMID 26379039, 2015). "Deletion of ARID1A in mouse intestines led to the development of colorectal carcinoma via a non-APC-dependent pathway." (PMID 38275587, 2023). "There is a study showing that inactivation of ARID1B in colorectal cancer cells that do not express ARID1A can further sensitize these cells to IR." (PMID 36605718, 2022). "The results show that in 5 of 46 cases of colorectal cancer (10.9%) no ARID1A protein expression was detectable." (PMID 36249060, 2022). "Treatment of colorectal cancer cell lines with TSA increased ARID1A expression in a cell line-dependent manner, suggesting that histone deacetylation is at least one factor contributing to ARID1A downregulation in colorectal cancer." (PMID 35611248, 2022). "The sensitizing effect of VE822 on colorectal cancer with and without ARID1A expression was evaluated in an ex vivo experimental setting." (PMID 36249060, 2022). "To determine the effects of SP-2577 on SWI/SNF-mutant cell viability, we performed drug-dose-response (DDR) studies with 72 h CellTiterGlo viability endpoints in SCCOHT (SMARCA4-/-), OCCC (ARID1A-/-), lung (SMARCA4-/-), kidney (SMARCB1-/-), and colorectal cancer cell lines (SMARCA4-/-)." (PMID 32649682, 2020). "ARID1A mRNA level was different in colorectal cancer cell lines and varied from almost nondetectable in SW48 to high expression level in HCT116 and HT-29/219." (PMID 32334542, 2020). "Our results showed no ARID1A protein expression in 38.8% (7/18) cases of colorectal cancer and 66.6% had no or low expression." (PMID 32334542, 2020). "Here, we investigated the effect of ARID1B knockdown on radiosensitivity in colorectal cancer (CRC) cell lines by measuring clonogenic survival after irradiation of cells with and without ARID1A mutation." (PMID 31796878, 2019). "RAD51 foci formation in ARID1A-proficient colorectal carcinoma (CRC) cell lines was not affected, except for HTC116." (PMID 31796878, 2019). "We therefore asked whether the mechanism of ARID1A and ARID1B synthetic lethality in HCT116 colorectal carcinoma cells identified in our study is conserved in OCCCs with naturally occurring ARID1A mutations." (PMID 28967863, 2017). "A relatively high mutation rate of ARID1A was reported in the colorectal cancer (10–40%), but it is not apparent whether DNA hypermethylation, and/or copy number variation (CNV) also are contributory in alteration of ARID1A expression." (PMID 32334542, 2020). "However, there has been no investigation on ARID1A epigenetic inactivation in colorectal cancer." (PMID 32334542, 2020). "Our method is able to identify the known driver genes for colorectal cancer; additionally, we also identified some driver genes not found by the MutSigCV study, such as COL12A1, MLL2, FAT4 and ARID1A." (PMID 26379039, 2015).